TFF3 (trefoil factor 3)
Diseases named in the same sentence as TFF3 in open-access papers (continued):
Sharing a sentence is not in itself a finding about the gene and the disease.
helminth infection (3 papers, 2010 to 2021). "While we were able to make advances by reporting infection, sex, and age-specific effects on TFF2 and TFF3 levels in human helminth infection, these studies do have some shortcomings that limit their interpretation." (PMID 34662329, 2021). "To further support the translational potential of TFFs as a biomarker of infection or therapeutic target, we evaluated the levels of TFF2 and TFF3 for the first time in human helminth infection in geographically distinct regions." (PMID 34662329, 2021). "Whereas, in the resistant mice, other proteins (such as Relm-β, Tff3, and angiogenin) may be retained and effectively concentrated at the sites of worm infection." (PMID 20138044, 2010).
kidney transplant (3 papers, 2018 to 2023). A surgical procedure in which one or both kidneys from a donor are implanted into a recipient. "In this study, we aimed to elucidate the roles of TFF3 overexpression in prostate tumorigenesis by knocking down the overexpressed TFF3." (PMID 30139961, 2018). "To investigate the role of TFF3 overexpression in prostate carcinogenesis, we examined the proliferation of PCa cells after the knockdown of overexpressed TFF3 by transfecting the PCa cell lines with TFF3-specific siRNA (siTFF3)." (PMID 30139961, 2018). "We also explored the molecular mechanisms behind its tumorigenic roles and determined that TFF3 is involved in prostate carcinogenesis via blocking the mitochondria-mediated apoptosis pathway." (PMID 30139961, 2018). "Taken together, the data support the hypothesis that the TFF3-mediated antiapoptotic pathway plays a role in prostate carcinogenesis." (PMID 30139961, 2018). "After observing the effects of TFF3 silencing on prostate tumorigenesis in PCa cell lines with TFF overexpression, we hypothesize that the overexpression of TFF3 is involved in prostate carcinogenesis via blocking mitochondria-mediated apoptosis." (PMID 30139961, 2018).
malaria (3 papers, 2022 to 2026). Malaria is a serious and sometimes fatal disease caused by a parasite that commonly infects a certain type of mosquito which feeds on humans. "In pediatric patients with malaria, elevated levels of trefoil factor 3 (TFF-3) and intestinal fatty acid binding protein (I-FABP), markers of intestinal injury, are associated with severe malaria and an increased risk of death." (PMID 37856470, 2023). "In the present study, we assessed intestinal injury in a well-characterized cohort of children with severe malaria and report elevated levels of markers of intestinal injury (TFF3 and I-FABP) that interacted with AKI and acidosis to increase in-hospital mortality." (PMID 36069443, 2022).
nematode infection (3 papers, 2011 to 2019). "The potential role of TFF3 during nematode infections has been related to mucosal defense and tissue restitution but it still remains unknown if TFF1 may also contribute to tissue repair." (PMID 21569362, 2011). "TFF3 is IL-4/IL-13-regulated and interacts with the mucin MUC2 (not on array) to alter mucus viscosity, with which it co-localises in human intestinal goblet cells, and up-regulation of both these mucus components has been associated with responses to nematode infection in mice." (PMID 21682880, 2011).
non-alcoholic fatty liver disease (3 papers, 2022 to 2025). "However, more recent research has linked TFF3 to cancer, colitis, gastric ulcers, diabetes mellitus, non-alcoholic fatty liver disease (NAFLD), and abnormalities of the CNS." (PMID 40943196, 2025). "Recent findings indicate that in pathological conditions such as cancer, colitis, gastric ulcers, diabetes mellitus, and non-alcoholic fatty liver disease, there are notable alterations in the expression profile and biological impacts of TFF3." (PMID 38666855, 2024).
oral squamous cell carcinoma (3 papers, 2017 to 2019). "The developed ELISA was employed to determine TFF3 in saliva samples of both healthy subjects and oral squamous cell carcinoma (OSCC) patients." (PMID 29151819, 2017). "It has been reported that TFF3 acts through EGFR to activate downstream pathways including p44/42MAPK, while the inhibition of p44/42MAPK specifically abrogated migratory properties of oral squamous-cell carcinoma cells stimulated by exogenous TFF341,42." (PMID 31685806, 2019). "In salivary gland tumors, a higher expression of TFF1, TFF2, and TFF3 was found, while in oral squamous cell carcinoma TFF2 and TFF3, but not TFF1, were downregulated with respect to healthy tissue." (PMID 29296124, 2017).
rectal cancer (3 papers, 2015 to 2019). A primary or metastatic malignant neoplasm that affects the rectum. "TFF3 is expressed in goblet cells in the intestines and the colon, and overexpression of TFF3 after chemoradiotherapy for rectal cancer is associated with a higher risk of relapse." (PMID 24934327, 2015). "Furthermore, the expression of TFF3 has been reported to be increased by chemo-radiotherapy, resulting in reduced sensitivity to treatment and higher risk of relapse in rectal cancer." (PMID 31835445, 2019). "Previously study showed that up-regulation of TFF3 after rectal cancer chemo-radiotherapy is an adverse prognostic factor." (PMID 28070169, 2017). "Upregulation of TFF3 after rectal cancer chemo-radiotherapy is an adverse prognostic factor." (PMID 28070169, 2017).
renal dysfunction (3 papers, 2014 to 2022). "We observed that plasma levels of GDF-15 and TFF3 are potential renal dysfunction markers in Chinese SLE patients." (PMID 33134397, 2020). "In conclusion, our data suggest that plasma levels of GDF-15 and TFF3 are potential renal dysfunction markers in SLE patients, but plasma levels of these cytokines were weakly or not correlated with the SLEDAI-2K." (PMID 33134397, 2020). "Our data suggest that plasma levels of GDF-15 and TFF3 are potential renal dysfunction markers in SLE patients, but plasma levels of these cytokines are not correlated with the SLEDAI-2K." (PMID 33134397, 2020). "Urine TFF3 is a sensitive and specific biomarker for tubular injury used to detect early renal dysfunction." (PMID 25031551, 2014). "Moreover, plasma levels of GDF-15 and TFF3 were highly positively correlated with clinical parameters of renal dysfunction." (PMID 33134397, 2020). "Urine TFF3 is a different indicator than serum levels and could also be a biomarker for the early detection of renal dysfunction." (PMID 25031551, 2014). "Urine TFF3 is a different indicator to serum levels and could also be a biomarker for the early detection of renal dysfunction." (PMID 25031551, 2014). "Although the roles of GDF-15 and TFF3 in SLE were not clear, our results suggest that the plasma levels of GDF-15 and TFF3 reflect the severity of renal dysfunction in SLE." (PMID 33134397, 2020).
steatosis (3 papers, 2019 to 2025). Increased lipid within the cytoplasm of cells. "It appears that the forced adenoviral overexpression of Tff3 has the same effect in mice suffering from steatosis." (PMID 40426854, 2025). "In WT female mice, hepatocytes with macrovesicular steatosis were also present and were more numerous than in Tff3-/- female mice." (PMID 36013467, 2022).
thyroid (3 papers, 2011 to 2022). "Several researchers revealed noticeable differences in Trefoil factor 3 (TFF3) between benign thyroid nodules and thyroid malignancy." (PMID 36276977, 2022). "Samples from PTC patients without thyroiditis showed high expression of TFF3 while PTC with thyroiditis high expression of CCDC80." (PMID 36077831, 2022).
type II diabetes (3 papers, 2023 to 2025). "In contrast, patients with type 2 diabetes and chronic kidney complications had significantly increased TFF3 concentrations in both serum and urine." (PMID 40426854, 2025). "Tff3−/− males had downregulated levels of triglyceride compared to WT males, suggesting that Tff3 deficiency could have a protective effect since it is known that elevated level of triglycerides in the serum can indicate the development of metabolic conditions, such as type 2 diabetes." (PMID 40426854, 2025). "Tff3 is moderately expressed in biliary epithelial cells and dramatic down-regulation of Tff3 expression was observed in a murine model of type II diabetes." (PMID 37628863, 2023). "Recent studies indicate trefoil factor 3 protein (Tff3), as a novel participant in these complex metabolic processes, represents a potential new target for metabolic conditions such as MAFLD and type II diabetes." (PMID 40426854, 2025).
ulcer (3 papers, 2021 to 2022). "TFF3 upregulation was found in mouse ulcer models and human ulcer patients, and was often associated with intestinal metaplasia." (PMID 34440733, 2021). "A significant increase in TFF3 mRNA was detectable as early as day 2 after ulcer induction; the level steadily increased at the ulcer margin after day 4 By 40 days, the TFF3 levels were elevated several hundred folds." (PMID 35039476, 2022).
acute myocardial infarction (2 papers, 2013 to 2021). Necrosis of the myocardium, as a result of interruption of the blood supply to the area. "This investigation demonstrated that the liver was able to respond to MI-R injury to mobilize its cells to the circulatory system and ischemic myocardium for mitigating myocardial infarction by releasing the cardioprotective factor TFF3." (PMID 34349157, 2021). "The TFF3−/− mice showed significantly higher levels of myocardial infarction at 1, 5, and 10 days after MI-R injury than the wildtype mice." (PMID 34349157, 2021). "Administration of recombinant TFF3 to the ischemic myocardium of the TFF3−/− mice immediately after coronary artery ligation increased the level of TFF3 in the ischemic myocardium and significantly reduced the level of myocardial infarction in reference to that with PBS administration." (PMID 34349157, 2021). "Administration of recombinant TFF3 mitigated acute myocardial infarction." (PMID 24204940, 2013).
Anaemia (2 papers, 2024 to 2026). "Also, it is plausible that the effect of severity of anaemia or RBCT may not have been detected due to wide variation in urine (I-FABP, L-FABP and TFF-3) and stool (Calprotectin) biomarker values documented in this study." (PMID 39649403, 2024).
atrophic gastritis (2 papers, 2018 to 2019). "Although serum TFF3 has been reported as a stable marker for gastric atrophy, assessment of TFF3 did not add further value to that of PG1." (PMID 31235543, 2019).
Atrophy (2 papers, 2014 to 2025). Any weakening or degeneration, especially through lack of use. "While the use of reverse stepwise analysis must be considered exploratory, the consistency with which TFF3 emerges as a strong independent predictor of atrophy is striking." (PMID 25072324, 2014).
cerebral infarcts (2 papers, 2013 to 2019). "Animals exposed to stroke showed that Tff3 deficient mice on a LS diet had more pronounced brain infarct volume." (PMID 31635131, 2019). "Administration of recombinant TFF3 to TFF3-/- mice significantly reduced the fraction of cerebral infarcts and mitigated the loss of the injured cerebral hemisphere." (PMID 24204940, 2013). "In all groups, toMCAO induced cerebral infarction; however, significant difference was only observed in the TFF3−/− LS group where toMCAO produced significantly larger infarction compared to WT LS mice." (PMID 31635131, 2019). "TFF3 was released into the circulation, alleviated cerebral cell death, mitigated caspase 3 activity, reduced the fraction of cerebral infarcts, and improved the motor function of the forelimbs." (PMID 24204940, 2013). "TFF3-/- mice exhibited a significantly smaller area of the injured right cerebral hemisphere or a smaller right-to-left hemisphere ratio at the maximal cerebral infarction site compared to wild-type mice notably at 10 and 30 days." (PMID 24204940, 2013). "TFF3-/- mice exhibited a significantly increased fraction of cerebral infarcts compared to wild-type mice at all observation times." (PMID 24204940, 2013). "Compared to wild-type mice, TFF3-/- mice exhibited a significantly higher activity of caspase 3 and level of cell death in the ischemic cerebral lesion, a larger fraction of cerebral infarcts, and a smaller fraction of the injured cerebral hemisphere, accompanied by severer forelimb motor deficits." (PMID 24204940, 2013).
cholangiocarcinoma (2 papers, 2013 to 2025). A carcinoma that arises from the intrahepatic biliary tree (intrahepatic cholangiocarcinoma) or from the junction, or adjacent to the junction, of the right and left hepatic ducts (hilar cholangiocarcinoma). "As secretory proteins, serum TFF3 levels have also been proposed as a screening marker for various cancers, including breast, gastric, prostate, pancreatic, and lung, and cholangiocarcinoma." (PMID 39955556, 2025).
chronic obstructive pulmonary disease (2 papers, 2019 to 2022). A chronic and progressive lung disorder characterized by the loss of elasticity of the bronchial tree and the air sacs, destruction of the air sacs wall, thickening of the bronchial wall, and mucous accumulation in the bronchial tree. "Under pathological conditions, TFF3 is increased in bronchoalveolar lavage (BAL) fluid from patients with chronic obstructive pulmonary disease (COPD) as well as in the serum and sputum of COPD and asthma patients." (PMID 36499686, 2022).
Cirrhosis (2 papers, 2017 to 2023). A chronic disorder of the liver in which liver tissue becomes scarred and is partially replaced by regenerative nodules and fibrotic tissue resulting in loss of liver function. "Single studies assessed the potential role of other novel biomarkers including TFF-3, GST, OPN, MCP-1, and TLR4; however, due to the lack of data, further evaluation of their utility in differential diagnosis of acute renal dysfunction among patients with cirrhosis." (PMID 38139297, 2023).
co-infection (2 papers, 2017 to 2021). "infections are protective during co-infection with an A/E enteropathogen, in association with parasite-induced release of β-defensins and TFF3 from IECs." (PMID 28622393, 2017). "Data from the present study establish that G. duodenalis co-infection with EPEC enhances intestinal epithelial beta-defensin and TFF3 production in a parasite cysteine protease-dependent manner, hence adding a novel role for G. duodenalis cathepsin-like cysteine proteases." (PMID 28622393, 2017). "Therefore, we sought to determine what effect co-infection of hookworm and Schistosoma, or either infection alone might have on TFF2, TFF3, and IL-33 levels in serum as compared to both endemic and non-endemic controls, accounting for age and sex as covariates." (PMID 34662329, 2021). "In addition, we propose that another mechanism leading to protection during a co-infection with A/E pathogens may involve a Giardia cysteine(s) protease(s)-dependent activation of host-defense via expression and secretion of AMPs such as HBD-2 and TFF3." (PMID 28622393, 2017).
Cognitive impairment (2 papers, 2020 to 2024). Abnormal cognition is characterized by deficits in thinking, reasoning, or remembering. "Likewise, plasma concentrations of myostatin, PI3, TFF3, and PAPPA have been shown to identify at-risk individuals with high accuracy and well before clinical signs of cognitive impairment appear." (PMID 38337499, 2024).
colorectal tumor (2 papers, 2019 to 2024). "The reason for this may be that blood vessels within the colorectal tumor tissue are sensitive to TFF3 and VEGF, TFF3 and VEGF induce vascular endothelial growth and promote angiogenesis." (PMID 38773485, 2024). "Consistent with previous reports in various cancers, we demonstrated that TFF3 promoted proliferation, survival, oncogenicity, migration and invasion of CMS4 CRC cells, and is required for full growth of CMS4 colorectal tumours in vivo." (PMID 31835445, 2019).
cystic fibrosis (2 papers, 2019 to 2022). Autosomal recessive disorder caused by pathogenic variants in the CFTR gene (cystic fibrosis transmembrane conductance regulator), which encodes a chloride and bicarbonate channel expressed in epithelial cells, and follow the diagnosis criteria. "Furthermore, in cystic fibrosis airways, TFF3 synthesis increased in surface goblet cells, whereas the elevated expression of TFF1 and TFF2 occurred in mucous cells of submucosal glands." (PMID 36499686, 2022). "Additionally, they reported direct binding of TFF3 onto the bacteria S. aureus and P. aeruginosa in sputum samples of patients with cystic fibrosis, which may contribute to the defense mechanisms of the innate immune system." (PMID 31683988, 2019).
diarrhoea (2 papers, 2022 to 2023). "Other DEGs that were down-regulated in the high-diarrhoea group include Ovar-DRB1, DQA, TREM2, TFF3, ITLN2, CD74, CCL5, and CCR3." (PMID 35140270, 2022).
end-stage renal disease (2 papers, 2015 to 2017). "Comparably, TFF3 levels have been shown to constantly increase during CKD progression to end-stage renal failure." (PMID 28355260, 2017).
glioblastoma (2 papers, 2017 to 2022). The most malignant astrocytic tumor (WHO grade IV). "However, the expression pattern and function of TFF3 in glioblastoma (GBM) have not been reported." (PMID 29100347, 2017).
hippocampal atrophy (2 papers, 2014 to 2018). "After additionally adjusting for baseline diagnosis, lower levels of TFF3 were still associated with higher hippocampal atrophy (P=0.007)." (PMID 25072324, 2014). "Lower levels of TFF3 were consistently associated with greater ventricular expansion (P<0.001), hippocampal atrophy rate (P<0.001) and whole brain atrophy rate (P<0.001) even after adjusting for baseline brain volumes, t-tau, p-tau, age, APOE status and sex." (PMID 25072324, 2014). "In exploratory reverse stepwise analyses, lower TFF3 was associated with higher rates of whole brain, hippocampal atrophy and ventricular expansion." (PMID 25072324, 2014). "The relationship between low TFF3 and increased hippocampal atrophy rate remained after adjustment for diagnosis." (PMID 25072324, 2014). "Lower levels of TFF3, VEGF and CrA and higher levels of CysC were associated with increased rates of brain atrophy; lower levels of TFF3 with increased ventricular expansion; and lower levels of TFF3 and higher levels of CysC with increased rates of hippocampal atrophy." (PMID 25072324, 2014). "In addition, adjusting for baseline diagnosis, TFF3 was the only analyte independently associated with hippocampal atrophy rate; and no analytes were (independently) associated with whole brain atrophy or ventricular expansion." (PMID 25072324, 2014).
intestinal tumors (2 papers, 2017 to 2024). "TFF3 is a secreted small peptide that supports intestinal tissue repair but is also involved in intestinal tumour progression and scattering." (PMID 28149533, 2017).
invasive ductal carcinoma (2 papers, 2014 to 2019). "A recent study has demonstrated that high TFF3 expression is associated with residual disease after neoadjuvant chemotherapy of invasive ductal carcinoma whereas low TFF3 expression is associated with a complete pathological response." (PMID 31658702, 2019).
ischemia (2 papers, 2021 to 2023). A hypoperfusion of the BLOOD through an organ or tissue caused by a PATHOLOGIC CONSTRICTION or obstruction of its BLOOD VESSELS, or an absence of BLOOD CIRCULATION. "While AKI in the acute setting may be a result of ischemia and decreased renal perfusion associated with critical illness, the specific elevation of TFF3 associated with eGFR decline implicates a more general pattern of tubular injury that underlies COVID mediated kidney dysfunction." (PMID 37308534, 2023).